ENSG00000221083
Synonyms: LOC124900452
Gene: Small nucleolar RNA gene on chromosome 1 (8,511,795 to 8,511,919, reverse strand). Ensembl gene ENSG00000221083.
Gene Ontology:
Biological process: RNA processing
Cellular component: nucleolus
Homologues: Orthologues: zebrafish SNORA77B (46% identical). Paralogues in human: SNORA77 (80% identical), SNORA77B (77% identical).